ZFP42 (ZFP42 zinc finger protein)
Description:
Involved in the reprogramming of X-chromosome inactivation during the acquisition of pluripotency. Required for efficient elongation of TSIX, a non-coding RNA antisense to XIST. Binds DXPas34 enhancer within the TSIX promoter. Involved in ES cell self-renewal (By similarity).
Synonyms: Zfp-42; REX-1; REX1; ZNF754
Tractability: PROTAC: UniProt records ubiquitination sites on it; ubiquitination databases record sites on it.
Gene: Protein-coding gene on chromosome 4 (187,994,044 to 188,007,005, forward strand). Ensembl gene ENSG00000179059.
Subcellular location: Nucleus
Gene Ontology:
Molecular function: protein binding; sequence-specific double-stranded DNA binding; DNA-binding transcription factor activity; DNA-binding transcription factor activity, RNA polymerase II-specific; RNA polymerase II cis-regulatory region sequence-specific DNA binding
Biological process: female gonad development; male gonad development; meiotic cell cycle; regulation of transcription by RNA polymerase II
Cellular component: cytoplasm; PcG protein complex; transcription regulator complex; nucleus
Genetic constraint (gnomAD): Loss-of-function variants: 1 observed, 0.24 expected, observed/expected ratio (o/e) 4.14. That is too few expected variants to judge how well the gene tolerates losing a copy. Missense variants: 438 observed, 399.17 expected, observed/expected ratio (o/e) 1.1, 90% interval 1.01 to 1.19. Synonymous variants: 175 observed, 155.23 expected, observed/expected ratio (o/e) 1.13, 90% interval 1 to 1.28.
Homologues: Orthologues: chimpanzee ZFP42 (98% identical), macaque ZFP42 (87% identical), rabbit ZFP42 (60% identical), dog ZFP42 (58% identical), rat Zfp42 (57% identical), rat Zfp42 (56% identical), mouse Zfp42 (53% identical), Drosophila melanogaster phol (33% identical), Caenorhabditis elegans ztf-17 (23% identical). Paralogues in human: YY1 (48% identical), YY2 (44% identical).
Diseases named in the same sentence as ZFP42 in open-access papers:
ZFP42 is named in the same sentence as 15 diseases in open-access papers, as found by Europe PMC text mining. Sharing a sentence is not in itself a finding about the gene and the disease. The quoted sentences say what the papers report.
lung carcinoma (4 papers, 2017 to 2025). "In this current study, we found that HOXA7 DNA methylation was correlated with higher NDI, and methylation of HOXA7, SOX17, ZFP42, HOXA9, CDO1 and TAC1was associated with advanced stage disease in lung cancer." (PMID 39107707, 2024). "Collectively, this study reveals that the methylation of 7 genes (TAC1, CDO1, HOXA9, ZFP42, SOX17, RASSF1A and SHOX2) has a big significance in the diagnosis of lung cancer and achieved a diagnostic model with high sensitivity and specificity." (PMID 38315228, 2024). "While many biomarkers have been shown to be viable for gastric and urinary cancers such as bladder and CRC, one study also reported a successful DNA methylation analysis (1.7) of a panel (CDO1, TAC1, HOXA7, HOXA9, SOX17, and ZFP42 promoters) to diagnose lung cancer." (PMID 40141826, 2025). "Here, we explored the significance of the DNA methylation of 7 genes including TAC1, CDO1, HOXA9, ZFP42, SOX17, RASSF1A and SHOX2 in the blood cfDNA samples in distinguishing lung cancer from benign nodules and healthy individuals." (PMID 38315228, 2024). "Here, we compared the DNA methylation status of 7 genes including TAC1, CDO1, HOXA9, ZFP42, SOX17, RASSF1A and SHOX2 in lung cancer cases with I–IV stages." (PMID 38315228, 2024). "To this end, we compared the DNA methylation status of 7 genes including TAC1, CDO1, HOXA9, ZFP42, SOX17, RASSF1A and SHOX2 in lung cancer cases with different stages." (PMID 38315228, 2024). "In this study, we explored the significance of the DNA methylation of 7 genes including TAC1, CDO1, HOXA9, ZFP42, SOX17, RASSF1A and SHOX2 in the blood cfDNA samples in distinguishing lung cancer from benign nodules and healthy individuals." (PMID 38315228, 2024). "Then, we explored the diagnosis value of the DNA methylation status of 7 genes including TAC1, CDO1, HOXA9, ZFP42, SOX17, RASSF1A and SHOX2 in lung cancer." (PMID 38315228, 2024). "In conclusion, despite these limitations, our meta-analysis advocates that methylated SOX17, CDO1, ZFP42, TAC1, FAM19A4, FHIT, MGMT, p16, and RASSF1A are useful biomarkers in the screening and auxiliary detection of lung cancer." (PMID 28644424, 2017). "Following a large literature review, we explored the performance of the DNA methylation of 7 genes including TAC1, CDO1, HOXA9, ZFP42, SOX17, RASSF1A and SHOX2 in the blood cfDNA samples in distinguishing lung cancer from benign nodules and healthy individuals." (PMID 38315228, 2024). "Moreover, we compared the DNA methylation status of 7 genes (TAC1, CDO1, HOXA9, ZFP42, SOX17, RASSF1A and SHOX2) in lung cancer cases from the mass and GGNs groups." (PMID 38315228, 2024). "Therefore, we advocate that methylated SOX17, CDO1, ZFP42, TAC1, FAM19A4, FHIT, MGMT, p16, and RASSF1A are useful in the screening and auxiliary detection of lung cancer." (PMID 28644424, 2017).
cervical cancer (3 papers, 2021 to 2024). A primary or metastatic malignant neoplasm involving the cervix. "In cervical cancer, ZFP42 promotes epithelial-mesenchymal transition (EMT)-induced metastasis by activating the JAK2/STAT3 signaling pathway." (PMID 39695095, 2024). "ZFP42 acts as an oncogene in prostate cancer, cervical cancer and glioblastoma multiforme, whereas ZFP42 is identified as a tumor suppressor gene in hepatocellular carcinoma and renal cell carcinoma." (PMID 39695095, 2024).
Hearing impairment (1 paper, 2021). A decreased magnitude of the sensory perception of sound. "To date, F11, MTNR1A, and ZFP42 have not been associated with hearing impairment or inner ear anomalies." (PMID 33418956, 2021).
non-small cell lung carcinoma (1 paper, 2023). A group of at least three distinct histological types of lung cancer, including non-small cell squamous cell carcinoma, adenocarcinoma, and large cell carcinoma. "High-frequency methylation profiles have been reported for several cancer-specific genes, including SOX17, TAC1, HOXA7, CDO1, HOXA9, and ZFP42, in both preoperative plasma and sputum samples from lymph node-negative stage I and IIA non-small cell lung cancer (NSCLC) patients." (PMID 37840147, 2023).
prostate carcinoma (1 paper, 2024). A carcinoma that arises from epithelial cells of the prostate gland. "ZFP42 activates the MEK/ERK pathway, promoting tumorigenesis in prostate cancer." (PMID 39695095, 2024).
teratocarcinoma (1 paper, 2014). A germ cell tumor characterized by the presence of an embryonal carcinoma component and a teratoma component. "The expression of the pluripotency-related protein Zfp42 (Rex1)—whose mRNA was upregulated in A2 SMA mESC-derived MNs —is repressed by RA in F9 teratocarcinoma cells." (PMID 25191843, 2014).
cancer (4 papers, 2017 to 2024). A tumor composed of atypical neoplastic, often pleomorphic cells that invade other tissues. "We observed CPNE7 was also distributed in the nucleus of cancer cells, implying it may regulate ZFP42 transcription." (PMID 39695095, 2024). "REX1 is also called zinc finger protein 42 (ZFP42) and has been studied in multiple cancer types." (PMID 33117795, 2020). "Zfp42 belongs to Myc-centered regulatory network, which is active in various cancers." (PMID 27894081, 2017). "We also found that c-JUN facilitates expression of pluripotent genes, such as Klf5, Zfp42, Dppa4 and Esrrb, which is consistent with previous observations that c-JUN plays a pivotal role in the maintenance of self-renewal in cancer stem cells." (PMID 27894081, 2017). "We also pointed out that NONO cooperated with CPNE7 to promote ZFP42 transcription and cancer growth and metastasis, which clearly defined its functional mechanism." (PMID 39695095, 2024). "Cancer development was observed by the modulation of genes involved in cell death (HIST1H1T, CASP14, and DNAJC3), cancer related genes (WNT8A and CASC8), gene expression (transcription) (ZNF570 and ZFP42), and metabolism of proteins (CALB2 and KLHDC3)." (PMID 31797963, 2019). "We observed CPNE7 and NONO were colocalized in the nucleus of cancer cells, implying they may jointly regulate the transcription of ZFP42." (PMID 39695095, 2024).
tumor (3 papers, 2022 to 2026). "The transcriptionlevel of most of the genes (with the exception of ZNF728, ZNF560, and ZFP42) inthe tumor is reduced by more than three-fold, to values comparable to those inother tissues." (PMID 36348719, 2022). "As expected, gramicidin significantly inhibited tumor growth and the expression of ZFP42." (PMID 39695095, 2024). "Emerging studies report that ZFP42 is also expressed in tumor cells." (PMID 39695095, 2024). "Moreover, ZFP42 knockdown inhibits tumor cell proliferation and migration while promoting apoptosis." (PMID 39695095, 2024). "RAM+ cells were governed by ZFP42 and IRF8 maintaining anti-tumor immunity, while RAM- cells controlled by ILF2 and ISL1 promoted metastasis and immune evasion, with RAM- malignant cells enriched in patients over 65 years and associated with immunotherapy resistance." (PMID 42304383, 2026).
adenocarcinoma (1 paper, 2024). A common cancer characterized by the presence of malignant glandular cells. "SOX17, TAC1, CDO1, HOXA9 and ZFP42 were the 5 genes that were identified in the Cancer Genome Atlas (TCGA) with highly prevalent DNA methylation in lung squamous and adenocarcinoma, but not in normal lung tissue." (PMID 38315228, 2024).
ZFP42 also shares sentences with these, for which no sentence is quoted: colorectal cancer (1 paper); colorectal tumours (1); glioblastoma multiforme (1); hepatocellular carcinoma (1); renal cell carcinoma (1); seminoma (1).